CES2 (carboxylesterase 2)
Diseases named in the same sentence as CES2 in open-access papers (continued):
Sharing a sentence is not in itself a finding about the gene and the disease.
pancreatic ductal adenocarcinoma (2 papers, 2019 to 2023). An infiltrating adenocarcinoma that arises from the epithelial cells of the pancreas. "A recent study has shown that CES2 can stimulate the expression of hepatocyte nuclear factor 4 (HNF4) protein, which helps to maintain the progenitor subtype of pancreatic ductal adenocarcinoma." (PMID 38020758, 2023).
prostate carcinoma (2 papers, 2025 to 2026). A carcinoma that arises from epithelial cells of the prostate gland. "hTERT-immortalized human ADSCs overexpressing carboxylesterase 2, combined with irinotecan, exhibited potent and tumor-selective anti-cancer effects against PC3, a castration-resistant prostate cancer model." (PMID 41296406, 2025).
steatosis (2 papers, 2017 to 2021). Increased lipid within the cytoplasm of cells. "Decreases in TAG content, reversal of histologically determined steatosis, and increases in serum ketone bodies suggest that human CES2 plays a similar role in vivo." (PMID 28099843, 2017). "Similar to our findings with human CES2 expression, overexpression of mouse CES2 decreased adiposity, improved glucose tolerance, and reversal of steatosis." (PMID 28099843, 2017). "In addition, downregulation of Ces2 is associated with NASH disease progression and high-fat-diet-induced steatosis." (PMID 34248683, 2021).
adenoma (1 paper, 2016). A neoplasm arising from the epithelium. "Further validation was performed by western blot analysis of 3 representative proteins (i.e. ACO2, CES2 and ANXA3), using paired CRC, adenoma and normal fresh-frozen tissues of 3 patients." (PMID 27661117, 2016).
colitis (1 paper, 2021). Inflammation of the colon. "Thus, colitis is associated with reduced CES2/Ces2 gene expression in the human and murine colons, respectively." (PMID 33872605, 2021). "To evaluate whether murine Ces2 gene members phenocopy the expression pattern of CES2 in the presence of colitis, we investigated colon samples from mice treated with DSS to induce colitis." (PMID 33872605, 2021).
colorectal adenocarcinoma (1 paper, 2005). The most common type of colorectal carcinoma. "Irinotecan is bioactivated to a more potent form via CES2 (carboxylesterase 2), and colorectal adenocarcinomas overexpressing CES2 are more sensitive to the drug." (PMID 15655543, 2005).
COVID-19 (1 paper, 2025). A disease caused by infection with severe acute respiratory syndrome coronavirus 2. "While it is well established that COVID-19 can broadly suppress xenobiotic metabolism pathways, the impact of SARS-CoV-2 infection on CES1 and CES2 activity remains underexplored, and experimental validation in hepatocytes or in vivo models needs to be performed." (PMID 40733041, 2025).
Crohn disease (1 paper, 2021). A gastrointestinal disorder characterized by chronic inflammation involving all layers of the intestinal wall, noncaseating granulomas affecting the intestinal wall and regional lymph nodes, and transmural fibrosis. "Intriguingly, we observed a significant decline in CES2 mRNA expression in colon biopsies of humans affected with ulcerative colitis, whereas levels were unchanged in patients with Crohn's disease." (PMID 33872605, 2021). "Remarkably, CES2 expression was significantly reduced in patients with ulcerative colitis but not in patients with Crohn’s disease." (PMID 33872605, 2021).
hyperglycaemia (1 paper, 2019). "In summary, we demonstrated that human UC-MSC infusions significantly attenuated hyperglycaemia, improved lipid metabolism, and ameliorated NAFLD in db/db mice, which may be associated with the upregulation of the HNF4α-CES2 pathway that promoted β-oxidation and inhibited lipogenesis in the liver." (PMID 31781248, 2019).
hyperlipidemia (1 paper, 2025). "Given the portal vein hepatic first pass metabolism, the levels of D and DA prior to hydrolysis by Cyp 2C19, 3A4 and/or CES2 could be high enough to directly inhibit liver ROCK1 to contribute to the anti-hyperlipidemia activity in the different animal models and in the human trial outcome." (PMID 39779619, 2025).
melanoma (1 paper, 2025). A malignant, usually aggressive tumor composed of atypical, neoplastic melanocytes. "The expression profiles of Ces2 isoforms also varied, with Ces2e being elevated in melanoma, while Ces2c was more abundant in normal skin." (PMID 39934865, 2025).
metabolic syndrome (1 paper, 2025). A cluster of metabolic risk factors for CARDIOVASCULAR DISEASES and TYPE 2 DIABETES MELLITUS. "In addition, a better understanding of the lipid and glucose homeostasis processes in which CES2 may be involved could provide clues on how to ameliorate aspects of metabolic syndrome." (PMID 39496863, 2025).
metastatic tumors (1 paper, 2020). "For example, CES2 harbors three SCNAs (loss of 6p/q and 13p along with gain of Xp/q) as common SCNAs that emerged before dissemination of metastatic tumors." (PMID 33017516, 2020).
nonalcoholic fatty liver disease (1 paper, 2019). "Murine hepatic carboxylesterase 2c (Ces2c) and the presumed human ortholog carboxylesterase 2 (CES2) have been implicated in the development of nonalcoholic fatty liver disease (NAFLD) in mice and obese humans." (PMID 30766961, 2019).
oral squamous cell carcinoma (1 paper, 2025). "For instance, CES2 disrupts lipid homeostasis, leading to mitochondrial dysfunction in oral squamous cell carcinoma." (PMID 41145471, 2025).
osteoporosis (1 paper, 2025). A condition of reduced bone mass, with decreased cortical thickness and a decrease in the number and size of the trabeculae of cancellous bone (but normal chemical composition), resulting in increased fracture incidence. "The results indicate that the expression level of the CYB5R4 gene has a notably higher influence on the osteoporosis diagnostic model compared to other factors, while the expression level of the CES2 gene has a lower impact on the osteoporosis diagnostic model relative to other factors." (PMID 40918403, 2025). "Alterations in CES2 expression in osteoporosis may indicate changes in bone marrow adiposity, influencing bone turnover and providing insights into the metabolic interplay within bone tissue." (PMID 40918403, 2025).
ovarian carcinoma (1 paper, 2024). A malignant neoplasm originating from the surface ovarian epithelium. "Chemotherapy combinated with ADSCs genetically engineered to express human carboxylesterase-2, can overcome drug resistance and exhibit survival benefits in ovarian cancer with intraperitoneal metastasis." (PMID 38643448, 2024).
psoriasis (1 paper, 2025). An autoimmune condition characterized by red, well-delineated plaques with silvery scales that are usually on the extensor surfaces and scalp. "Since the compound is intended for topical use in psoriasis, where DMF has been shown to be harmful, and CES2 expression was previously observed in keratinocytes, the authors subjected both DMF and the new compound to in vitro test-tube incubation with CES2." (PMID 41471022, 2025).
tumor (24 papers, 2002 to 2025). "Furthermore, high CES2 expression in tumor tissue was associated with longer overall survival in resectable and borderline resectable PDAC patients who underwent neoadjuvant FOLFIRINOX treatment." (PMID 30867471, 2019). "Carboxylesterases CES1 and CES2 in the normal range should correspond to zero resistance of the tumour cells to camptothecin compounds, topoisomerase I inhibitors." (PMID 40347057, 2025). "This dual role highlights the importance of understanding the tumor-specific transcriptional regulation of the CES2 gene." (PMID 41438085, 2025). "After xenograft experiment, we further confirmed that GDNT can restrict tumor growth in mice injected with H1299 cells by activating CES2 to enhance metabolism of MMF into MPA." (PMID 38419324, 2024). "CES2 immunoreactivity was evaluated separately in CCA tumor cells and in the tumoral stroma component (see Material & Methods section)." (PMID 30867471, 2019). "IHC confirmed that CES2 is expressed in tumor cells as well as in the stromal cell compartment, suggesting that both cellular compartments are capable of activating CPT-11 to SN-38." (PMID 31795490, 2019). "Patients showing any CES2 expression in tumor cells had a significantly better overall survival compared to negative cases (p = 0.008)." (PMID 30867471, 2019). "Here, we evaluated CES2 expression by immunohistochemistry in tumor cells and tumoral stroma in a well-characterized and comprehensive cohort of non-liver fluke associated CCA using a CES2 antibody." (PMID 30867471, 2019). "Although CES2 has been shown to express within tumor tissue, our data demonstrate that Hst can synergize the tumor inhibition of CPT-11 through negative regulation on tumor STAT3 activity." (PMID 29963254, 2018). "In primary tumor tissues, CES2 expression tended to be higher than that observed in liver metastasis tissues (p = 0.05)." (PMID 25198900, 2014). "CES2 expression also varies among different cancer types and individuals, so differences in CES2 activity in tumors may influence the response of tumor tissue to specific drugs." (PMID 39496863, 2025). "Since the enhancement of TurboID biotinylation efficiency by BME in living cells depends on the expression of CES1 and CES2, we compared the expression of these genes in the common tumor cell lines (HeLa, HEK293T, and U937) and in normal endothelial, fibroblast, epithelial, and epidermal cells." (PMID 41402538, 2025). "Exploratory immunohistochemistry was undertaken to assess how CES2 tumour expression might affect CAP7.1 efficacy, given its role in the conversion of CAP7.1 to etoposide." (PMID 33121007, 2020). "Thus, patients exhibiting high CES2 expression show a distinct tumor immune profile with increased presence of CD8+ and FOXP3+ immune cells." (PMID 30867471, 2019). "Recent results have shown that the expression of CES2 is related to tumor staging." (PMID 25198900, 2014). "However, in addition to expression in tumour cells, immune cell infiltrates in the immediate tumour vicinity were shown to express high levels of CES2, suggesting that in some patients, adjacent tissues may provide a relevant source of CES2." (PMID 33121007, 2020). "Here, the prodrug would penetrate the tumor, CPT-11 would be released, and then converted to its active metabolite SN-38 by carboxylesterase 2 (CE2)." (PMID 38898077, 2024). "Hydrolysis of CPT-11 by human carboxylesterase 2 (CE2) generates SN-38, a topoisomerase I inhibitor that is the active anti-tumor agent." (PMID 26509550, 2015). "Therefore, if cancer cells themselves actively express CES2, the efficacy of CPT‐11 may be increased by conversion within the tumor itself." (PMID 32961616, 2020).
tumor (continued). "Neither DNA copy number nor mRNA expression of CES2 gene has any alteration between normal and cancerous colorectal or gastric tissues in the TCGA datasets, suggesting that targeting CES2 may not potentiate tumor growth." (PMID 29963254, 2018).
cancer (13 papers, 2015 to 2025). A tumor composed of atypical neoplastic, often pleomorphic cells that invade other tissues. "Low expression of carboxylesterase 2 (CES2) has been implicated in the progression of NAFLD, inflammation, and cancer." (PMID 33872605, 2021). "Carboxylesterase 2 (CES2) is instrumental for conversion of ester-containing prodrugs in cancer treatment." (PMID 30867471, 2019). "The positive regulation of CLCA1 and CES2 were both lost from normal to cancer, and thus may result in reduced expression of two targets, which could further inhibit proliferation or induce apoptosis." (PMID 35421923, 2022). "The intersection of differentially expressed genes (DEG) and our list of candidate genes, resulted in 12 elements including cancer associated genes (NRAS, MYC, and VEGFA), circadian drug targets (SOD2 and CES2) and core-clock and ECCN genes (AHR, CREB1, CSNK2A1, NFIL, NPAS2, NR1D1, and PER3)." (PMID 32295075, 2020). "However, CES2 expression is downregulated in many types of cancer." (PMID 32961616, 2020). "In accordance, two recent studies linked low CES2 expression in cancer cell lines to DAG (and lysoPC) accumulation, which could be reversed upon CES2 overexpression, albeit these studies show a divergent impact of CES2 expression levels and the overall survival of cancer patients." (PMID 37059417, 2023). "The expression of CEBPA was decreased in cancer samples in GSE54129 dataset and formed DRLs with CLCA1, CES2." (PMID 35421923, 2022). "Notably, CES2 and CYP3A5 serve as pivotal regulators in drug metabolic pathways across various cancer types." (PMID 38540686, 2024). "Furthermore, the anti-cancer effect of MMF on LUAD was found to be potentiated in combination with GDNT, which was mechanically mediated by CES2." (PMID 38419324, 2024). "Upregulation of CES2 gene expression and hence the conversion of CPT‐11 to SN‐38 in the cancer tissue itself may increase drug efficacy." (PMID 32961616, 2020). "A recent study demonstrated a negative correlation of CES2 expression and intracellular lysophosphatidylcholine (lysoPC) and DAG levels in cancer cell lines and another study discovered lysoPC (16:0) as a PPARg ligand." (PMID 37059417, 2023).
metabolic disease (6 papers, 2017 to 2025). A congenital disorder (due to inherited enzyme abnormality) or acquired (due to failure of a metabolically important organ) disorder resulting from an abnormal metabolic process. "The top-ranked downregulated DEG in females is a Ces2 member (p = 0.00029), a key protector of metabolic disease involving glucose metabolism." (PMID 41034487, 2025). "In humans, low hepatic CES2 expression and activity have been demonstrated in NASH patients and obese individuals, suggesting a role for CES2 in metabolic disease development." (PMID 37059417, 2023).
infection (5 papers, 2015 to 2025). The state of being infected such as from the introduction of a foreign agent such as serum, vaccine, antigenic substance or organism. "Transcript levels of some of the key DMEs were upregulated in the liver of the infected mice, 8 weeks post-infection like Nat2, Cyp2e1, Slco1b2, Ces1, Ces2, and Aadac (upregulated by almost 2–3-fold)." (PMID 41358489, 2025). "In contrast, no changes were observed in the survival of ces-2(gk1020), ztf-11(ok646), or atf-6(ok551) animals fed E. faecium before infection." (PMID 35263319, 2022).
CES2 also shares sentences with these, for which no sentence is quoted: hepatoma (3 papers); liver disease (2); lung adenocarcinoma (2); metastatic colorectal cancer (2); adenocarcinoma (1); atherosclerosis (1); bladder cancer (1); cholangiocarcinoma (1); cocaine use disorder (1); cyst (1); gastric cancer (1); Hypertension (1); injury (1); liver cirrhosis (1); liver fibrosis (1); tuberculosis (1); ulcerative colitis (1).